VCAM1 (vascular cell adhesion molecule 1)
Diseases named in the same sentence as VCAM1 in open-access papers (continued):
Sharing a sentence is not in itself a finding about the gene and the disease.
tumor (continued). "In both models, histologic examination confirmed that VCAM-MPIO were localized to VCAM-1–positive vessels at the tumor margins." (PMID 35312755, 2022). "In line with this, E-selectin, ICAM-1, and VCAM-1 are upregulated on the surface of the activated endothelial cells, which attract the different immune cells to the tumor lesion." (PMID 35327461, 2022). "First, stem cells or bone marrow-derived progenitor cells express VLA-4, allowing for progenitor cell homing to VCAM-1 present in the tumor periphery." (PMID 36497180, 2022). "In this context, the involvement of VCAM-1 in both pro-inflammatory and pro-metastasis processes provides an entry point of anti-tumor activity through endothelial modulation." (PMID 35408794, 2022). "Adhesion molecules such as ICAM1 and VCAM-1 on tumor vessels are also upregulated, leading to increased extravasation of T cells to tumor sites." (PMID 36612124, 2022). "Independent ILC3 functions are more correlated to the adhesion molecules on the tumour vasculature, VCAM1 (vascular adhesion molecule 1), promoting tumour infiltration from leukocytes." (PMID 35557940, 2022). "Already discussed anti-VCAM-1 aptamer conjugated SPIONs, apart from demonstrating favorable tumor imaging ability, were also investigated for tumor growth suppression." (PMID 35463298, 2022). "Analysis of endothelial VCAM-1 distribution indicated a greater concentration of VCAM-1–positive vessels in proximity to the tumor edge." (PMID 35312755, 2022). "The interface between tumor and surrounding normal brain tissue exhibited elevated endothelial VCAM-1 expression and increased microvessel density." (PMID 35312755, 2022). "Previous data indicate that CCL3/CCR1 signaling regulates tumor cell macrophage interactions that, once established, deliver a survival signal to the tumor cells through engagement of αV-integrin expressed on MAMs and VCAM1 on the tumor cell." (PMID 36077870, 2022). "Previous studies suggested that VCAM-1-dependent motility is an essential factor for tumor metastatic developments." (PMID 34760697, 2021). "Abnormal VCAM-1 expression was found to induce disseminated tumor cell binding to osteoclasts expressing the α4β1 integrin, resulting in bone metastasis." (PMID 35118073, 2021). "Endothelial Notch1 signaling upregulates VCAM1 expression, which promotes the adhesion of tumor cells to the endothelium, extravasation and lung colonization, as shown by using VCAM1-blocking antibodies." (PMID 34073394, 2021). "The surface of the tumor endothelium expresses a glycoprotein known as vascular cell adhesion molecule-1 (VCAM-1) that is involved in the process of angiogenesis." (PMID 34866166, 2021). "This activation also serves as an adhesive ligand that captures VCAM-1 + metastatic tumor cells, thereby promoting LN metastasis." (PMID 34241649, 2021). "VEGF also restricts the migration of Teff cells into the tumor microenvironment by downregulating the expression of adhesion molecules including ICAM-1 and VCAM-1 on tumor-associated endothelial cells." (PMID 33746989, 2021). "RT-induced IFN-γ increased the VCAM-1 expression on tumor vasculature to facilitate T cell infiltration." (PMID 35095911, 2021). "MP6-XT22 was shown to decrease co-expression of CD31 and VCAM1 in the tumor areas compared to those in untreated vehicle control (score 3.2 vs 1.8, p = 0.03) and increase survival (log-rank test, p = 0.0008)." (PMID 33853689, 2021). "Blocking VCAM-1 reduces the number of thrombotic/thromboembolic events as well as infiltration of TAM and tumor-associated neutrophils and prolonged overall survival of treated mice." (PMID 34638420, 2021). "In the total of 84 HPV-regulated genes, only four genes (EGFR, SNF, UBD, and VCAM1) were differentially expressed when compared with HPV− tumor." (PMID 34646755, 2021).
tumor (continued). "Targeting of the endothelium is achieved by using the αvβ3 integrin and vascular cell adhesion molecule-1 (VCAM-1), and of the extracellular tumor stroma by matrix metalloproteases (MMPs)." (PMID 34439219, 2021). "We assess the co-expression of the CD31 and VCAM1 on endothelial cells in the tumor and adjacent morphologically normal cortical brain tissue in this mouse model." (PMID 33853689, 2021). "It has been shown that vascular cell adhesion molecule-1 (VCAM-1) recruits and activates osteoclasts resulting in a vicious cycle of bone destruction and tumor expansion." (PMID 34064392, 2021). "As the metastatic process is highly inefficient, circulating tumor cells (CTC) interact for example with neutrophils by forming CTC–neutrophil clusters via vascular cell adhesion molecule 1 (VCAM-1) to expand metastatic potential." (PMID 33540843, 2021). "Their study demonstrated that VCAM-1 secreted from CAFs activated AKT and MAPK signaling pathways, enhancing tumor growth and invasion in a reversible manner (with VCAM-1 blocking antibodies)." (PMID 33808627, 2021). "There is significantly increased co-expression of the CD31 and VCAM1 in tumor areas compared to that in adjacent normal brain tissue or non-injected contralateral normal brain (scores 3.2 vs 1, p = 0.0004)." (PMID 33853689, 2021). "Of note, tumor-derived vascular cell adhesion molecule 1 (VCAM-1) has been shown to promote transition from indolence to overt metastasis by recruiting CD11b+ monocytes and increasing osteoclast activity." (PMID 34803925, 2021). "Anti-angiogenic therapy: Pro-angiogenic growth factors produced by tumour cells can downregulate the expression of a collection of adhesion molecules (e.g., VCAM-1 and ICAM-1), inhibiting extravasation of T lymphocytes across the tumour endothelium." (PMID 33917287, 2021). "H. pylori infection was shown to elevate VCAM1 expression in CAFs, which indicated tumor invasion and progression." (PMID 34745945, 2021). "Deconvolution of the non-tumor kidney samples with BisqueRNA47 estimated that the proportion of PT_VCAM1 cells was 2.6%, which is consistent with our snRNA-seq and snATAC-seq estimates." (PMID 33850129, 2021). "At the early stage of bone metastasis, vascular cell adhesion molecule-1 (VCAM1) and the integrin family are important molecules mediating the relationship between tumor cells and osteoclasts." (PMID 33869189, 2021). "Murine PDAC tissues showed VCAM-1 expression in tumor cells, while some stromal cells also showed positive staining." (PMID 33273652, 2020). "Both in vitro cell viability and bioluminescence assays, and in vivo BLI and MRI investigations confirmed that these target specific aptamers effectively blocked the VCAM-1 and IL4Rα signals and suppressed the tumor progression in 4T1-bearing mice." (PMID 32751068, 2020). "Anti-inflammatory drug, resveratrol, inhibits VCAM-1 expression on tumour-activated LSEC and reduced hepatic melanoma metastases by 75% in a murine model." (PMID 32982772, 2020). "The concentration of TNF-α and immunoglobulin-like cell adhesion molecules like ICAM-1 and VCAM-1 will trigger the chemotaxis which is directly related to the metastasis of tumor cells by vascular penetration." (PMID 32764400, 2020). "Vascular cell adhesion molecule 1 (VCAM-1) is upregulated on LECs by tumor inflammation and was shown to regulate lymphatic vessel permeability." (PMID 32244922, 2020). "TNF-α is also involved in the increased expression of adhesion molecule (such as VCAM-1 or P-selectin) on the endothelium of tumor vessels, leading to the necrosis of tumor." (PMID 32102503, 2020). "Our lab has shown that TXA2 derived from platelets interacting with tumor cells intravascularly induces the expression of E-selectin and VCAM-1 by endothelial cells in the proximity of tumor cells-platelets emboli." (PMID 33042789, 2020).
tumor (continued). "Cell viability and luciferase assays showed that both anti-VCAM-1 and anti-IL4Rα aptamers favor the depletion of cancer cells and limit tumor progression." (PMID 32751068, 2020). "We, therefore, examined the expression levels of VCAM-1, which has a pivotal role in tumor metastasis." (PMID 32079335, 2020). "In this study, DAWT tissue exhibited low miR-181 expression, which would be expected to lead to reduced VCAM-1 inhibition, thereby increasing the likelihood of tumor cell invasion and migration in DAWT." (PMID 32766179, 2020). "Functionally, recent evidence has demonstrated the importance of VCAM1-integrin interactions in tumor metastasis in an inflammatory environment." (PMID 32793471, 2020). "The presence of senescent ECs increased inflammatory chemokine secretion and VCAM1 expression, which attracted tumor cells (TCs) of MBC to ECs and facilitated the TC/EC interaction." (PMID 32993785, 2020). "VCAM1 was identified as a Notch1ICD direct target in tumor endothelial cells that positively regulated the opening of EC junctions and homing for tumor cells, facilitating transmigration and colonization." (PMID 33198378, 2020). "Vascular cell adhesion molecule-1 (VCAM-1) is a transmembrane immunoglobulin found expressed on the surfaces of tumor endothelial cells." (PMID 33202648, 2020). "Wild-type mice injected with tumour cells were found to have significantly increased expression of VCAM-1 and E-selectin on LSEC." (PMID 32982772, 2020). "The in vivo therapeutic efficacy evaluated in tumor-bearing mice confirmed the therapeutic efficacy of anti-VCAM-1 and anti-IL4Rα aptamers that were conjugated to SPION as assessed by monitoring tumor growth and inhibition using noninvasive BLI and MRI." (PMID 32751068, 2020). "Accordingly, in a previous report, CRT has shown to promote tumor lymphocyte infiltration and enhance the efficacy of immunotherapy, ascribing such effect to the upregulation of adhesion molecules such as ICAM-1 and VCAM1 in tumor endothelium." (PMID 33584695, 2020). "Our previous study also showed that ICAM-1 and VCAM-1 are involved in tumor growth and migration and the adhesion of cancer cells to other organs." (PMID 32466580, 2020). "Inflammatory chemokine secretion and VCAM1 expression were significantly increased in senescent ECs, resulting in tumor cell (TC) chemotaxis and TC/EC interactions." (PMID 32993785, 2020). "The results revealed that both aptamers act as anti-tumor drugs by blocking the expression of VCAM-1 and IL4Rα receptors." (PMID 32751068, 2020). "Vascular cell adhesion molecule-1 (VCAM-1) is an immunoglobulin-like glycoprotein that is also expressed on the surface of the tumor endothelium and is involved in angiogenesis by interacting with vascular endothelial cells." (PMID 32974385, 2020). "In contrast to the results from in vitro experiments, we observed VCAM-1 overexpression increased tumor volume by 48% compared to the cells with control vector." (PMID 33273652, 2020). "The up-regulation of adhesion molecules such as ICAM1 and VCAM1 by tumor vasculature plays a critical role in the recruitment of leukocytes to the tumor tissue and activation of endothelial cell." (PMID 32340193, 2020). "Platelet microthrombi on tumor cells induce endothelial cell expression of E-selectin, VCAM-1, and VAP-1 in lung endothelial cells and anti-coagulant therapy dramatically reduces endothelial activation to basal levels." (PMID 33042789, 2020). "Mechanistically, iNOS induced endothelial activation by upregulating vascular cell adhesion protein-1 (VCAM-1) expression and stimulated T-cell recruitment to the tumor tissue through enhanced synthesis of the major Th1 recruiting chemokine, RANTES." (PMID 33005420, 2020). "Increased ICAM-1 and VCAM-1 expression by the tumor vasculature in response to the pro-inflammatory agent CpG-ODN correlated with improved CD8+ T cell trafficking in a mouse model of pancreatic islet cell carcinoma (RIP1-Tag5)." (PMID 33262763, 2020).
tumor (continued). "We chose ICAM1 and VCAM1, two cell-cell adhesion molecules required for the transmigration step of tumor metastasis." (PMID 32090682, 2020). "Imaging tumor angiogenesis has been performed targeting vasculature cell adhesion molecule-1 (VCAM-1), a protein involved in the adhesion of lymphocytes, monocytes, eosinophils and basophils to the vascular endothelium." (PMID 33353213, 2020). "Agonistic antibodies targeting CD137 increase E-selectin, ICAM-1, and VCAM-1 surface expression on tumor vessels." (PMID 33262763, 2020). "The highly angiogenic nature of HCC is associated with increased classical growth factors such as VEGF and PDGF, whilst classical adhesion molecules such as ICAM-1 and VCAM-1 are preferentially expressed on tumour tissue." (PMID 32982772, 2020). "Anti-VCAM1 and anti-IL4Rα aptamers, specific to VCAM-1 and IL4Rα receptors overexpressed in 4T1-Luc2 tumor-bearing mice, were used as diagnostic and therapeutic tools." (PMID 32751068, 2020). "In line with this, subcutaneous allografts of the VCAM-1 knocked-down cancer cells showed delayed tumor growth compared to cancer cells with scramble shRNA." (PMID 33273652, 2020). "We observed differences in the effect of VCAM-1 expression on tumor growth and gemcitabine resistance between in vitro 2D and in vivo 3D models." (PMID 33273652, 2020). "Subsequently, the results of the tumor-endothelial cell adhesion assay supported that CRC cells upregulating VCAM1 exhibited stronger adhesion to HUVECs." (PMID 32793471, 2020). "In BC, the overexpression of VCAM-1 on tumor cells correlates with early relapse and poor patient outcome." (PMID 31340603, 2019). "Increased expression of adhesion molecules—intercellular adhesion molecule 1 (ICAM1) and VCAM1—in tumor vessels enables tumor infiltration by T lymphocytes." (PMID 31261963, 2019). "We therefore analyzed the expression of a number of adhesion-associated proteins (E-selectin, N-cadherin, ICAM-1, VCAM-1; CD44, integrin α4, integrin α5, integrin β1) in tumor cells and endothelial cells using Western blot." (PMID 30717801, 2019). "99mTc-cAbVCAM1-5 can therefore be used as a preclinical tool to evaluate the role of VCAM-1 expression by tumor cells in tumor development and metastasis." (PMID 31340603, 2019). "Either NETs or VCAM1 adhesion molecules seem to be important in the interaction between neutrophils and circulating tumor cells." (PMID 31616408, 2019). "These inflammatory mediators trigger the recruitment of macrophages, which then promote tumor cell survival and increase the vascular permeability, possibly by transmitting the pro-survival signals via VCAM-1 expressed on tumor cell surface." (PMID 30927923, 2019). "Tumor-induced lymphangiogenesis promotes metastasis to the lymph node through the activation of α4β1 integrin on lymphatic endothelium, which binds to VCAM1-positive tumor cells." (PMID 31552050, 2019). "In the past few years, growing interest into tumorigenicity and metastatic processes has led to the identification of VCAM-1 as a key actor for tumor growth, metastasis and angiogenesis." (PMID 31340603, 2019). "Reportedly, after the arrival into the lung (pulmonary metastases account for 66% of distant metastases in HNSCC) tumor–platelet aggregates attached to ECs express tissue factor (TF) to stimulate the expression of VCAM-1 and VAP-1." (PMID 30927923, 2019). "These MAMs allow the extravasation of mouse tumor cells by secreting the chemokine ligand CCL3 and CSF-1 that facilitates metastatic seeding of breast cancer cells in the lung and potentially VCAM-1 that transmits survival signals to these tumor cells." (PMID 30832375, 2019). "For example, it was shown that vessels in the proximity of tumor lesions show expression of VCAM-1, ICAM-1, and other CAMs in different BrM models." (PMID 31396225, 2019).
tumor (continued). "Visualization of tumor endothelial cells that express vascular cell adhesion molecule-1 (VCAM-1) has been described using anti-VCAM-1 nanobody decorated microbubbles 91, and also radiotracer variants of this nanobody are available 100,101." (PMID 31695800, 2019). "VCAM1 is one of five genes (CXCL12, MMP2, MMP11, VCAM1, and MME), which were associated with tumor progression, angiogenesis, and metastasis." (PMID 31731625, 2019). "In the two mouse models of TNBC, SPECT imaging of VCAM-1 was successfully performed and the signal originated from the tumor was found to reflect hVCAM-1 expression by cancer cells rather than mVCAM-1 expression by the tumor stroma." (PMID 31340603, 2019). "In breast cancer models, tumor cells mimic the inflammatory state of the endothelium via endogenous expression of VCAM1, which tethers them to macrophages expressing α4β1 integrin that promote metastasis to the lung." (PMID 31497019, 2019). "The aberrant expression of VCAM-1 on dormant tumor cells in bone marrow was shown to recruit α4β1-expressing osteoclast progenitors during bone metastasis." (PMID 31552050, 2019). "For example, in a mouse model of melanoma, NKp46+ innate lymphoid cells (ILCs) upregulate vascular adhesions such as ICAM1 and VCAM1, which facilitate the infiltration of additional immune cells with anti-tumor functions." (PMID 31497019, 2019). "In bone, VCAM-1 expressing tumor cells binds to α4β1 integrin-expressing osteoclast progenitors to mediate osteolytic metastasis." (PMID 31340603, 2019). "ICAM‐1 and VCAM‐1 play an important role in promoting adhesion of inflammatory sites, controlling tumour progression and metastasis and regulating immune response." (PMID 30950217, 2019). "VCAM-1 has been shown to be involved in immune evasion and allows a strong interaction of its ligand VLA4 on monocytes and tumor-associated macrophages, recruiting them to metastatic lungs." (PMID 31607931, 2019). "Treatment with aspirin, SC-560, and picotamide also reduced the extent of endothelial activation as indicated by E-selectin and VCAM-1 expression in vessels adjacent to platelet–tumor cell aggregates." (PMID 30907747, 2019). "CAFs-induced macrophages infiltration was suppressed when VCAM-1 was knocked down in tumor cells, indicating an important role of VCAM-1 in CAFs-induced TAMs recruitment." (PMID 30894509, 2019). "It was shown using the TC-1 lung epithelial cancer model that tumors with high VCAM-1 expression were devoid of CD8+ tumor-specific T cells." (PMID 31695800, 2019). "In BC, VCAM-1 expression on tumor cells is an important actor for metastatic colonization of lungs and bones." (PMID 31340603, 2019). "The direct interaction of VCAM-1 with its ligand Very-Late Antigen -4 (VLA-4) expressed on leukocytes allows tumor cell survival in lungs and consequently lung metastasis." (PMID 31340603, 2019). "Patients with higher secretion of PIGF, TIE-2, ICAM-1 or VCAM-1 from their tumour explants displayed higher nodal status, reflective of a more aggressive cancer phenotype." (PMID 31217905, 2019). "The inhibition of β1-integrin or VCAM-1 sensitizes tumor cells to chemotherapy, making integrin inhibition a viable therapeutic approach to prevent metastasis." (PMID 31552050, 2019). "Several types of tumor cells express α4β1 integrin and the interaction with its ligand VCAM-1 increases transendothelial migration and contributes to metastasis to distant organs." (PMID 31338363, 2019). "VCAM-1 has been found to play a pivotal role in adhesion of cancer cells to the vascular endothelium and mediates specific tumor-stromal interactions, leading to metastasis of VCAM-1-expressing cells to lung, bone and brain." (PMID 31374991, 2019). "We compared expression of VCAM-1 in lungs of animals treated with vehicle or DABK, as VCAM-1 plays an important role in the metastatic process mediating tumor cell adhesion to the endothelium." (PMID 31607931, 2019).